TRNT1 (tRNA nucleotidyl transferase 1)
Description:
Nucleotidyltransferase that catalyzes the addition and repair of the essential 3'-terminal CCA sequence in tRNAs, which is necessary for the attachment of amino acids to the 3' terminus of tRNA molecules, using CTP and ATP as substrates. tRNA 3'-terminal CCA addition is required both for tRNA processing and repair. Promotes tRNA repair and recycling downstream of the ribosome-associated quality control (RQC) pathway by mediating addition of the tRNA 3'-terminal CCA following cleavage by ANKZF1 and repair by ELAC1. Also involved in tRNA surveillance by mediating tandem CCA addition to generate a CCACCA at the 3' terminus of unstable tRNAs and tRNA-like transcripts. While stable tRNAs receive only 3'-terminal CCA, unstable tRNAs beginning with GG are marked with CCACCA and rapidly degraded. The structural flexibility of RNA controls the choice between CCA versus CCACCA addition: following the first CCA addition cycle, nucleotide-binding to the active site triggers a clockwise screw motion, producing torque on the RNA. This ejects stable RNAs, whereas unstable RNAs are refolded while bound to the enzyme and subjected to a second CCA catalytic cycle. [Isoform 2]: Adds 2 C residues (CC-) to the 3' terminus of tRNA molecules instead of a complete CCA end as isoform 1 does (in vitro).
Synonyms: CGI-47; MtCCA; CCA1; RPEM; SIFD
Tractability: Small molecule: a structure with a bound ligand is known; it has a binding pocket of medium quality. PROTAC: ubiquitination databases record sites on it; its protein half-life has been measured.
Gene: Protein-coding gene on chromosome 3 (3,126,364 to 3,153,435, forward strand). Ensembl gene ENSG00000072756.
Subcellular location: Mitochondrion; Cytoplasm; Nucleus
Subcellular location (Human Protein Atlas): Mitochondria
Pathways (Reactome):
Metabolism of RNA: tRNA processing in the mitochondrion; tRNA processing in the nucleus
Gene Ontology:
Molecular function: CCA tRNA nucleotidyltransferase activity; CCACCA tRNA nucleotidyltransferase activity; protein homodimerization activity; tRNA binding; 5'-3' RNA polymerase activity; ATP binding; nucleotidyltransferase activity; RNA binding
Biological process: mitochondrial tRNA 3'-end processing; rescue of stalled ribosome; tRNA 3'-terminal CCA addition; tRNA surveillance; tRNA 3'-end processing; RNA processing
Cellular component: catalytic complex; cytoplasm; cytosol; mitochondrion; nucleus; mitochondrial matrix; nucleoplasm
Genetic constraint (gnomAD): Loss-of-function variants: 39 observed, 41.35 expected, observed/expected ratio (o/e) 0.94, 90% interval 0.73 to 1.23. The upper end of that interval is the gene's LOEUF score, 1.23, which puts it in group 5 of 6, group 1 being the genes least tolerant of losing a copy. Missense variants: 550 observed, 466 expected, observed/expected ratio (o/e) 1.18, 90% interval 1.1 to 1.27. Synonymous variants: 176 observed, 160.38 expected, observed/expected ratio (o/e) 1.1, 90% interval 0.97 to 1.24.
Gene-disease validity (ClinGen):
ClinGen rates the evidence that TRNT1 causes each of these diseases.
congenital sideroblastic anemia-B-cell immunodeficiency-periodic fever-developmental delay syndrome (autosomal recessive): Definitive. Congenital sideroblastic anemia -B cell immunodeficiency- periodic fever-developmental delay syndrome is a form of constitutional sideroblastic anemia, characterized by severe microcytic anemia, B-cell lymphopenia, panhypogammaglobulinemia and variable neurodegeneration.
Homologues: Orthologues: chimpanzee TRNT1 (99% identical), macaque TRNT1 (97% identical), mouse Trnt1 (93% identical), pig TRNT1 (93% identical), dog TRNT1 (92% identical), rat Trnt1 (92% identical), guinea pig TRNT1 (92% identical), rat LOC100911093 (92% identical), rabbit TRNT1 (85% identical), zebrafish trnt1 (67% identical), tropical clawed frog trnt1 (63% identical), Drosophila melanogaster CG2100 (47% identical), and 1 more.
Diseases named in the same sentence as TRNT1 in open-access papers:
TRNT1 is named in the same sentence as 61 diseases in open-access papers, as found by Europe PMC text mining. Sharing a sentence is not in itself a finding about the gene and the disease. The quoted sentences say what the papers report.
developmental delay (16 papers, 2015 to 2026). "Sideroblastic anemia, immunodeficiency, periodic fevers, and developmental delay (SIFD) is an autosomal recessive syndrome caused by biallelic loss-of-function variant of tRNA nucleotidyl transferase 1 (TRNT1)." (PMID 36729249, 2023). "Sideroblastic anemia with B-cell immunodeficiency, periodic fevers, and developmental delay (SIFD) is a serious autosomal recessive syndrome caused by biallelic mutations in cytosine-cytosine-adenosine tRNA nucleotidyltransferase 1 (TRNT1)." (PMID 36937953, 2023). "For example, sideroblastic anemia with B-cell immunodeficiency, fever, and developmental delay (SIFD) is an inherited recessive disease with a mutation in tRNA nucleotidyltransferase 1 (TRNT1)." (PMID 35885000, 2022). "Sideroblastic anemia with B cell immunodeficiency, periodic fever, and developmental delay (SIFD) is caused by biallelic loss of function mutation in TRNT1 gene leading to a defect in cytoplasmic and mitochondrial tRNA." (PMID 32737687, 2020). "We have recently described a novel form of congenital sideroblastic anemia that is associated with B-cell immunodeficiency, periodic fevers and developmental delay (SIFD) in which we identified mutations in TRNT1 and demonstrated that these mutations are disease causing." (PMID 27317422, 2016). "Recently, a cohort of patients exhibiting SIFD (Sideroblastic anemia associated with immunodeficiency, periodic fevers and developmental delay) were reported to carry mutations in TRNT1, with the range of clinical severity correlating with the degree of TRNT1 loss of function." (PMID 25806043, 2015). "Sideroblastic anemia with B-cell immunodeficiency, periodic fevers, and developmental delay (SIFD), a rare multisystemic syndrome, occurs due to loss-of-function mutations in the tRNA nucleotidyl transferase 1 (TRNT1) gene." (PMID 41795040, 2026). "One such disorder, sideroblastic anemia with B-cell immunodeficiency, periodic fevers, and developmental delay (SIFD), is caused by mutations in the tRNA-nucleotidyltransferase enzyme TRNT1." (PMID 41019077, 2025). "We have previously reported that partial loss-of-function mutations in TRNT1 cause a novel disease termed SIFD (sideroblastic anemia with B-cell immunodeficiency, periodic fevers, and developmental delay; SIFD)." (PMID 37239403, 2023). "For Patient 6147, diagnosis of homozygous variants in TRNT1 (OMIM#616084; Sideroblastic anemia with B-cell immunodeficiency, periodic fevers, and developmental delay) led to palliative care consultation and a change in ‘code status' to ‘Allow Natural Death'." (PMID 35141181, 2021). "Recently, mutations in TRNT1 were detected in patients with syndromic CSA that was associated with B cell immunodeficiency, periodic fevers, and developmental delay (SIFD)." (PMID 25985931, 2015). "TRNT1, as an enzyme necessary for the synthesis of the 3′-terminal CCA sequence in tRNA molecules, can lead to developmental delay, sideroblastic anemia, periodic fever, retinitis pigmentosa, B-cell immunodeficiency, and other diseases when it is abnormal." (PMID 34630514, 2021).
sideroblastic anemia (16 papers, 2015 to 2026). "TRNT1, while not currently associated with cancer, is known to harbor mutations that cause sideroblastic anemia." (PMID 40563552, 2025). "TRNT1 has not been associated with any cancer thus far, although its mutation is responsible for causing congenital disease and sideroblastic anemia." (PMID 40563552, 2025).
retinitis pigmentosa (10 papers, 2016 to 2024). Retinitis pigmentosa (RP) is an inherited retinal dystrophy leading to progressive loss of the photoreceptors and retinal pigment epithelium and resulting in blindness usually after several decades. "A previous study reported wide range of phenotypes with TRNT1 mutations both in childhood and adult onset retinitis pigmentosa, encephalopathy, hepatosplenomegaly and pancreatic insufficiency." (PMID 33484326, 2021). "TRNT1 mutations cause a spectrum of symptoms ranging from a childhood-onset complex disease with manifestations in most organs to an adult-onset isolated retinitis pigmentosa presentation." (PMID 29980628, 2018). "Retinal organoids established in 3D culture using Retinitis Pigmentosa patient-derived hiPSCs with mutations in TRNT1 (tRNA nucleotidyl transferase 1) showed altered autophagy activity, including an increase in LC3II levels and in elevated oxidative stress." (PMID 28800101, 2017). "Our report highlights that TRNT1 mutations cause a spectrum of disease ranging from a childhood-onset complex disease with manifestations in most organs to an adult-onset isolated retinitis pigmentosa presentation." (PMID 27370603, 2016). "Recently, hypomorphic mutations in TRNT1 were also found to cause rare non-syndromic retinitis pigmentosa with erythrocytic microcytosis." (PMID 27317422, 2016).
Immunodeficiency (8 papers, 2015 to 2025). Failure of the immune system to protect the body adequately from infection, due to the absence or insufficiency of some component process or substance. "Mutations in TRNT1 cause congenital sideroblastic anemia, immunodeficiency, fevers, and developmental delay (SIFD)." (PMID 29980628, 2018). "Given this, more research into the wide-ranging effects of TRNT1-related immunodeficiencies is required." (PMID 41019077, 2025). "While the link between TRNT1 deficiency and mitochondrial dysfunction is clearly established, its connections to SIFD-mediated immune dysfunction are more elusive and require further study." (PMID 41019077, 2025). "The clinical summaries of SIFD syndrome herein provided may be a useful tool to select patients with autoinflammatory syndromes and immunodeficiencies to direct specific testing for TRNT1 gene and therefore starting a more appropriate treatment according to the current knowledge." (PMID 35984545, 2023).
breast carcinoma (4 papers, 2021 to 2025). "We further explored the specific mutation types and loci of TRNT1 in breast cancer, with missense mutations being the primary type of genetic alteration." (PMID 41001838, 2025). "To investigate the expression and prognostic significance of TRNT1 in BC, we performed IHC analysis using breast cancer TMAs." (PMID 41001838, 2025). "TRNT1 appears to modulate protein activity through post‐translational mechanisms, as supported by both pan‐cancer and breast cancer‐specific analyses." (PMID 41001838, 2025). "We analysed the correlation between TRNT1 expression and lymphocyte infiltration, immunoinhibitors, and immunostimulators in breast cancer, and for each part, 4 main results were provided." (PMID 41001838, 2025). "Given the observed significant relationship between TRNT1 expression and breast cancer prognosis, we selected BC as the focus for further investigation." (PMID 41001838, 2025). "This study aims to explore the potential significance of TRNT1 in cancer, particularly in breast cancer (BC) progression and prognosis." (PMID 41001838, 2025). "Seven genes were shared between prostate and positive breast cancer responders (TRNT1, NUFIP1, TDG, HSPA8, OTUD6B, RBM12, and DENND3)." (PMID 35520391, 2022). "Therefore, it is critical to further investigate the role of TRNT1 in malignant tumours, including breast cancer." (PMID 41001838, 2025). "Therefore, future studies should focus on investigating the role of TRNT1 in various breast cancer subtypes and conducting animal model experiments to more accurately assess its role in the onset and progression of breast cancer." (PMID 41001838, 2025). "Additionally, we used breast cancer tissue microarrays and various in vitro cell‐based experimental techniques to investigate the biological function of TRNT1 in breast cancer and the signalling pathways it may involve." (PMID 41001838, 2025). "While these data provide initial evidence for the potential role of TRNT1 in breast cancer, the lack of in vivo animal model validation remains a limitation." (PMID 41001838, 2025). "Furthermore, our research only provides an initial investigation into the expression and function of TRNT1 in breast cancer, without further exploration of its role in different breast cancer subtypes." (PMID 41001838, 2025).
colorectal cancer (4 papers, 2020 to 2025). A primary or metastatic malignant neoplasm that affects the colon or rectum. "A comparison of gene expression profiles between African American and Caucasian American colorectal cancer patients revealed significantly lower expression of TRNT1 in the African American cohort, which is associated with higher incidence and mortality rates of colorectal cancer in this population." (PMID 41001838, 2025). "Moreover, TRNT1 has been implicated in oncogenesis through gene expression studies of colorectal cancer." (PMID 41001838, 2025). "The altered expression of TRMO has been observed in patients with thyroid carcinoma, while altered TRNT1 expression was seen in colorectal cancer patients." (PMID 40563552, 2025). "TRNT1 was also identified in a differential gene expression study comparing colorectal cancer patients of African American and European origins." (PMID 32471101, 2020). "The TRNT1 was shown to be downregulated in the cohort of African American patients, suggesting a link with higher incidence and mortality of colorectal cancer seen in African Americans." (PMID 32471101, 2020).
anemia (2 papers, 2020 to 2025). A reduction in the number of red blood cells, the amount of hemoglobin, and/or the volume of packed red blood cells. "Morpholino-mediate TRNT1 knockdown recapitulated anemia and sensory organ defects that are seen in SIFD patients, as well as decreased CCA addition to tRNA." (PMID 32471101, 2020).
metabolic syndrome (2 papers, 2016 to 2020). A cluster of metabolic risk factors for CARDIOVASCULAR DISEASES and TYPE 2 DIABETES MELLITUS. "Since some of the symptoms associated with SIFD appear to be related to metabolic syndrome, we were interested in determining how the patient-derived TRNT1 mutations affect mitochondrial biology, and we focused our studies on mitochondrial processes in patient-derived fibroblasts." (PMID 27317422, 2016).
thyroid carcinoma (2 papers, 2025). "In contrast, TRNT1 expression was significantly downregulated in cancers such as kidney chromophobe (KICH), KIRC, and thyroid carcinoma (THCA) (all p < 0.05)." (PMID 41001838, 2025).
Ataxia (1 paper, 2020). Ataxia refers to impaired coordination of voluntary muscle movement. "Another significant finding is the reduced availability of the mitochondrial transfer RNA (tRNA) nucleotidyl transferase (Trnt1) whose disruption in genome-wide association studies (GWAS) is associated with cerebellar developmental delay, ataxia, and reduced cellular respiration." (PMID 33141759, 2020).
clear cell renal cell carcinoma (1 paper, 2025). "Conversely, total TRNT1 protein expression levels were lower in clear cell renal cell carcinoma (RCC) and uterine corpus endometrial carcinoma (UCEC)." (PMID 41001838, 2025).
colon cancer (1 paper, 2025). "We found that compared to normal tissues, the total TRNT1 protein expression levels were significantly higher in BC, ovarian cancer (OC), colon cancer (CC), LUAD, PAAD, and LIHC (all p < 0.05)." (PMID 41001838, 2025).
Mitochondrial encephalopathy (1 paper, 2021). "Mutation in TRNT1 and SUCLA2 has been implicated in patients with mitochondrial encephalopathy." (PMID 33484326, 2021).
paraganglioma (1 paper, 2025). A benign or malignant neoplasm arising from paraganglia located along the sympathetic or parasympathetic nerves. "Specifically, elevated TRNT1 expression was associated with poor prognosis in BC, KIRC, LIHC, pheochromocytoma and paraganglioma (PCPG)." (PMID 41001838, 2025).
retinal disease (1 paper, 2018). "Furthermore, GRIPT was able to identify three novel retinal disease genes recently published, i.e., POMGNT1 (p = 3.95 × 10−15), TRNT1 (p = 6.25 × 10−8) and HGSNAT (p = 2.10 × 10−7)." (PMID 30477545, 2018).
Sepsis (1 paper, 2016). Sepsis is defined as life-threatening organ dysfunction caused by a dysregulated host response to infection. "TRNT1 deficiency produces a complex multisystem disease which can be confused with overwhelming sepsis given the febrile episodes with raised inflammatory markers." (PMID 27370603, 2016).
trypanosomiasis (1 paper, 2021). Infection with protozoa of the genus trypanosoma. "Additional genes highlighted in our study were CFH, TRNT1, IL5RA, MGAT4C and NTS, which could be also relevant for the trypanosomiasis resistance in cattle." (PMID 34351956, 2021).
infection (4 papers, 2013 to 2023). The state of being infected such as from the introduction of a foreign agent such as serum, vaccine, antigenic substance or organism. "Due to recurrence of severe infection by acute respiratory syndrome-coronavirus-2, genetic testing was conducted and a mutation in TRNT1 was found." (PMID 36729249, 2023).